RAPGEF6 (Rap guanine nucleotide exchange factor 6)
Description:
Guanine nucleotide exchange factor (GEF) for Rap1A, Rap2A and M-Ras GTPases. Does not interact with cAMP.
Synonyms: PDZ-GEF2; PDZGEF2; RA-GEF-2; KIA001LB; RAGEF2
Tractability: Antibody: UniProt places it where antibodies can reach, with high confidence; its Gene Ontology location is reachable by antibodies, with high confidence. PROTAC: ubiquitination databases record sites on it; its protein half-life has been measured.
Gene: Protein-coding gene on chromosome 5 (131,423,921 to 131,635,234, reverse strand). Ensembl gene ENSG00000158987.
Subcellular location: Cytoplasm; Cell membrane
Subcellular location (Human Protein Atlas): Cytosol; Centrosome
Gene Ontology:
Molecular function: GTP-dependent protein binding; guanyl-nucleotide exchange factor activity; phosphatidic acid binding; protein binding; small GTPase binding
Biological process: establishment of endothelial intestinal barrier; positive regulation of microvillus assembly; neuron projection development; Rap protein signal transduction; Ras protein signal transduction; regulation of GTPase activity; signal transduction; small GTPase-mediated signal transduction
Cellular component: apical plasma membrane; cytosol; endocytic vesicle; plasma membrane; cytoplasm
Genetic constraint (gnomAD): Loss-of-function variants: 51 observed, 157.25 expected, observed/expected ratio (o/e) 0.32, 90% interval 0.26 to 0.41. The upper end of that interval is the gene's LOEUF score, 0.41, which puts it in group 1 of 6, group 1 being the genes least tolerant of losing a copy. Missense variants: 1,541 observed, 1,850.9 expected, observed/expected ratio (o/e) 0.83, 90% interval 0.8 to 0.87. Synonymous variants: 642 observed, 631.12 expected, observed/expected ratio (o/e) 1.02, 90% interval 0.95 to 1.09.
Homologues: Orthologues: chimpanzee RAPGEF6 (99% identical), macaque RAPGEF6 (97% identical), dog RAPGEF6 (95% identical), pig RAPGEF6 (93% identical), guinea pig RAPGEF6 (92% identical), mouse Rapgef6 (91% identical), rat Rapgef6 (91% identical), rabbit RAPGEF6 (89% identical), tropical clawed frog rapgef6 (74% identical), zebrafish rapgef6 (54% identical). Paralogues in human: RAPGEF2 (66% identical), SOS1 (14% identical), SOS2 (14% identical), RASGRF2 (13% identical), RASGRF1 (12% identical), RAPGEF4 (12% identical), RAPGEF3 (11% identical), RAPGEF5 (11% identical), RAPGEF1 (10% identical), RALGDS (10% identical), RASGRP1 (10% identical), RASGRP4 (9% identical), and 12 more.
Diseases named in the same sentence as RAPGEF6 in open-access papers:
RAPGEF6 is named in the same sentence as 30 diseases in open-access papers, as found by Europe PMC text mining. Sharing a sentence is not in itself a finding about the gene and the disease. The quoted sentences say what the papers report.
schizophrenia (11 papers, 2011 to 2026). A major psychotic disorder characterized by abnormalities in the perception or expression of reality. "Conditional knockout of either RAPGEF2 or RAPGEF6 in mice caused hyperlocomotion and deficits in learning and memory, which have been likened to symptoms observed in schizophrenia patients." (PMID 38463630, 2024). "At the cellular level, deletion of RAPGEF6 in mice displayed impaired neuronal activity in the hippocampus and amygdala, which are implicated in schizophrenia." (PMID 38463630, 2024). "Rap1 has previously been identified as interacting with candidate schizophrenia susceptibility gene, Rapgef6, disrupting amygdala function in mice." (PMID 31920576, 2019). "A recent study showed that Rapgef6 knock-out mice exhibited impaired function of the amygdala and hippocampus, brain regions that are implicated in schizophrenia pathophysiology." (PMID 27390776, 2016). "Rapgef6 deletion mice were most impaired in hippocampal and amygdalar function, brain regions implicated in schizophrenia pathophysiology." (PMID 26057047, 2015). "In human genetic studies of schizophrenia, we uncovered copy-number variants in RAPGEF6 and RAPGEF2 genes." (PMID 26057047, 2015). "Moreover, we show that Rapgef6, a close Rapgef2 homolog implicated in the etiology of schizophrenia, shares some of these functions with Rapgef2 from the examination of Rapgef2/6 double-knockout mice." (PMID 27390776, 2016). "Rapgef6 was investigated via a mouse model because it was implicated in schizophrenia risk." (PMID 26057047, 2015). "Additionally, RAPGEF2, RAPGEF6, and Rap1 are essential for the development of neural progenitor cells, which has recently been hypothesized as a risk factor for schizophrenia." (PMID 38463630, 2024). "Copy number variations in RAPGEF2 and RAPGEF6, which belong to a well conserved PDZ-RAPGEF family, are associated with schizophrenia." (PMID 38463630, 2024). "The behavioral phenotype described here supports the utility of Rapgef6 deletion as a model of neuropsychiatric disease, particularly schizophrenia." (PMID 26057047, 2015). "The accumulating results indicated that the RAPGEF6 gene has been established to perform a fundamental role in spermatogenesis, schizophrenia, and neuro psychiatric disorders in mice, indicating that RAPGEF6 is essential for the reproductive development in mice." (PMID 31137587, 2019). "Moreover, human genetic studies in a cohort of schizophrenia patients showed strong genetic association of rare inherited copy number variations involving RAPGEF2 and RAPGEF6 with schizophrenia." (PMID 29747665, 2018). "Genetic data from a variety of schizophrenia studies converge onto the RAPGEF6 locus." (PMID 26057047, 2015). "The results provide a deeper understanding of the role of the amygdala in schizophrenia and suggest that RAPGEF6 may be a novel therapeutic target in schizophrenia." (PMID 26057047, 2015). "Therefore, it is of interest to further characterize the physiological functions of the Cdk5-dependent regulation of Rap1 signalling via RapGEF2 and RapGEF6 in psychiatric disorders such as schizophrenia." (PMID 25189171, 2014). "In conclusion, although there were differences in their brain morphology and the magnitude of the behavioral abnormalities, Rapgef2-cKO mice and Rapgef6-KO mice exhibited hyperlocomotion phenotype and working-memory defect, both of which could be recognized as schizophrenia-like behavior." (PMID 29747665, 2018). "Therefore, we performed the prepulse inhibition test to investigate whether Rapgef2-cKO mice and Rapgef6-KO mice exhibited schizophrenia-like phenotype." (PMID 29747665, 2018). "As Rapgef6 is both a plausible functional and genetic candidate for schizophrenia risk, we performed a comprehensive analysis of mice lacking Rapgef6 to uncover its role in synaptic plasticity and behavioral paradigms dependent on learning, as well as neurite architecture." (PMID 26057047, 2015).
schizophrenia (continued). "Although deficiency of this gene has previously been linked to schizophrenia, no MIM phenotype entry currently associates RAPGEF6 with a defined clinical condition." (PMID 42274819, 2026).
male infertility (2 papers, 2018 to 2019). The inability of the male to effect fertilization of an ovum after a specified period of unprotected intercourse. "Knockout of another GEF, RapGEF6, results in male infertility, and accounts for reduced testis size as well as reduced sperm count and motility." (PMID 30360518, 2018).
angina pectoris (1 paper, 2025). The symptom of paroxysmal pain consequent to MYOCARDIAL ISCHEMIA usually of distinctive character, location and radiation. "In addition, especially the lead SNP rs6596024 near RAPGEF6 was associated with CVD phenotypes, such as coronary revascularization, angina pectoris, and ischaemic heart disease." (PMID 40701953, 2025).
Anxiety (1 paper, 2015). Intense feelings of nervousness, tension, or panic often arise in response to interpersonal stresses. "Finally, Rapgef6 mice were mildly hyperactive by measurements of locomotion and rearing and had reduced anxiety-like behavior." (PMID 26057047, 2015).
diffuse type adenocarcinoma (1 paper, 2023). An adenocarcinoma characterized by the presence of a diffuse cellular infiltrate which is composed of poorly cohesive cells with minimal or no glandular formations. "RapGEF6 exon 21A was more expressed in invasive diffuse-type adenocarcinomas, where NOVA2 levels were higher compared with other histotypes." (PMID 37175811, 2023).
Intellectual disability (1 paper, 2026). "Structural variation data from DECIPHER further indicate that copy-number variants involving RAPGEF6 are primarily associated with intellectual disability and micrognathia." (PMID 42274819, 2026).
neuroblastoma (1 paper, 2026). Neuroblastoma (NB) is the most common solid, extracranial childhood tumor. "In addition, RAPGEF6 expression progressively increased during retinoic acid-induced neuronal differentiation of SK-N-BE neuroblastoma cells, supporting a potential role of this gene in neuronal maturation processes." (PMID 42274819, 2026).
cancer (4 papers, 2011 to 2025). A tumor composed of atypical neoplastic, often pleomorphic cells that invade other tissues. "Tumors with higher size/extension (T2, T3, T4 according to the TNM classification of malignant tumors) show higher levels of RapGEF6 exon 21A compared with smaller ones (T1, T1a, T1b)." (PMID 37175811, 2023). "Importantly, cancer patients with high RapGEF6 exon 21A expression show shorter overall survival compared with patients displaying low or medium RapGEF6 exon 21A expression." (PMID 37175811, 2023). "Based on the essential role played by small GTPases (and their regulators) during angiogenesis, including the maintenance of endothelial integrity, as well as in cancer progression and metastasis, we focused our attention on the newly identified NOVA2 target RapGEF6." (PMID 37175811, 2023).
tumor (4 papers, 2011 to 2024). "Collectively, our data are in line with the possibility that the NOVA2/RapGEF6 circuit in tumor ECs contributes to the phenotypical and functional vascular aberrancies observed in GC patients." (PMID 37175811, 2023). "Moreover, a positive and statistically significant correlation was observed between NOVA2 and RapGEF6 exon 21A expression levels in primary tumor samples." (PMID 37175811, 2023). "Finally, we found that the AS of the Rap Guanine Nucleotide Exchange Factor 6 (RapGEF6), a newly identified NOVA2 target, is altered in GC patients and associated with NOVA2 expression, tumor angiogenesis, and poor patient outcome." (PMID 37175811, 2023). "However, the elucidation of the NOVA2/RapGEF6 circuit’s functional role in tumor vasculature requires further studies." (PMID 37175811, 2023).
RAPGEF6 also shares sentences with these, for which no sentence is quoted: breast carcinoma (2 papers); mental disorder (2); adult-onset Still disease (1); autism (1); colorectal carcinoma (1); COVID-19 (1); epilepsy (1); gastric cancer (1); Hypertension (1); ischaemic heart disease (1); keratosis (1); laryngeal paralysis (1); lung carcinoma (1); metabolic disorder (1); Micrognathia (1); Obesity (1); ovarian carcinoma (1); personality disorder (1); pulmonary disorder (1); retinitis pigmentosa (1); Splenomegaly (1).